GLS (glutaminase)
Diseases named in the same sentence as GLS in open-access papers (continued):
Sharing a sentence is not in itself a finding about the gene and the disease.
atherosclerosis (5 papers, 2023 to 2026). A disease characterized by the build-up of fatty material and calcium deposition in the arterial wall resulting in partial or complete occlusion of the arterial lumen. "In early-stage atherosclerosis, genes such as ATP7A, GLS, DLD, ATP7B, and PDHA1 are highly expressed, whereas in later stages, the expression levels of FDX1, CDKN2A, SLC31A1, and MTF1 increase." (PMID 39519014, 2024). "In GSE132561, GSE28829, and GSE120521, the ROC curves of FDX1, GLS, and SLC31A1 also verified that both had a high value for classification of the atherosclerosis stage." (PMID 37442861, 2023). "Furthermore, cuproptosis-related genes ferredoxin 1 (FDX1), solute carrier family 31 member 1 (SLC31A1), and glutaminase (GLS) are crucial in the onset and advancement of atherosclerosis." (PMID 40861271, 2025). "Therefore, CDKN2A, GLS, and MTF1 possess therapeutic potential for atherosclerosis." (PMID 39519014, 2024).
autoimmune disease (5 papers, 2017 to 2025). A disorder resulting from loss of function or tissue destruction of an organ or multiple organs, arising from humoral or cellular immune responses of the individual to their own tissue constituents. "In autoimmune diseases, dysregulated expression of the glutaminase enzyme GLS1 drives increased acetyl-CoA production, leading to enhanced histone acetylation at the Il17a promoter, thereby promoting Th17 and γδT17 cell differentiation." (PMID 40155378, 2025).
celiac disease (5 papers, 2015 to 2024). An autoimmune genetic disorder with an unknown pattern of inheritance that primarily affects the digestive tract. "Glutamine deamination, produced by the activity of glutaminase, has a central role in the immune pathogenesis of celiac disease and has been found to be implicated in autoimmune responses caused by various toxic substances and different pathogens." (PMID 38535307, 2024). "We have previously shown an association between celiac disease (CD) and amino acid metabolism including the gene glutaminase (GLS)." (PMID 36369023, 2022). "Untreated celiac disease (CD) patients have increased levels of blood glutamine and a lower duodenal expression of glutaminase (GLS)." (PMID 36369023, 2022). "In our patients, GLS gene expression was significantly decreased 2-fold compared to controls and a decreased GLS activity has previously been observed in the intestine of untreated celiac disease patients." (PMID 26123480, 2015). "In biopsies from celiac disease patients, minor allele carriers of the INSR rs7254060 SNP showed decreased INSR gene expression levels (INSR rs7254060; p = 0.003) and minor GLS rs6741418 carriers showed decreased GLS gene expression levels (GLS rs6741418; p = 0.009)." (PMID 26123480, 2015). "Seven genes were down-regulated in the biopsies of celiac disease patients, among them NTS down-regulated 3.6 fold and the INSR, APPL2, ADCY9, GLS, HSPB1 and KIF13A 1.5-2.2 fold in the patient group (p < 0.001)." (PMID 26123480, 2015). "Two of our eleven selected genes (GLS and PPP1R12B) map within celiac disease genome-wide significant loci." (PMID 26123480, 2015). "It is conceivable that anti-tissue glutaminase antibodies become negative in celiac disease patients adhering to diet." (PMID 35109858, 2022). "The differential expression of NTS and PPP1R12B indicate a potential role for smooth muscle contractility and cell proliferation, whereas other genes like GLS, NCALD and INSR suggests involvement of nutrient signaling and energy homeostasis in celiac disease pathogenesis." (PMID 26123480, 2015). "The differential expression of NTS and PPP1R12B indicate a potential role for smooth muscle contractility and cell proliferation in celiac disease, whereas other genes like GLS, NCALD and INSR suggests involvement of nutrient signaling and energy homeostasis in celiac disease pathogenesis." (PMID 26123480, 2015).
Hyperglycemia (5 papers, 2016 to 2024). An increased concentration of glucose in the blood. "This is significant because inhibitors of glutaminase, the first enzymatic step in glutaminolysis, are in development for the treatment of cancer and hyperglycaemia." (PMID 31053703, 2019). "The commercially available asparaginases possesses 3–10% intrinsic glutaminase activity, which often produces several side effects including pancreatitis, hyperglycemia, neurological seizures and various hypersensitivity reactions." (PMID 26891220, 2016). "The GLS amounts were not altered in MIC26 KO cells when compared with respective WT cells grown in normoglycemia and hyperglycemia." (PMID 39393820, 2024).
ischemia (5 papers, 2016 to 2025). A hypoperfusion of the BLOOD through an organ or tissue caused by a PATHOLOGIC CONSTRICTION or obstruction of its BLOOD VESSELS, or an absence of BLOOD CIRCULATION. "Treatment with CB839, a glutaminase inhibitor, reversed ischemia-induced microglial activation, inflammatory response, and exosome release." (PMID 32117296, 2020). "Glutaminolysis may also impact inflammatory cells; T cells exhibited metabolic reprogramming during IRI, with upregulated glutaminase activity during the ischemia period and a decline during reperfusion." (PMID 40546823, 2025). "Moreover, APC/C-Cdh1 down-regulation and subsequent glutaminase accumulation may contribute to the generation of excitotoxic environments in ischemia." (PMID 27514492, 2016).
lupus (5 papers, 2021 to 2025). "GLS1 is essential for Th17 cell differentiation, as shown in studies correlating GLS with SLE, and modulating GLS1 expression improves disease progression in lupus-prone MRL/lpr mice." (PMID 39388708, 2025). "Glutaminase expression is controlled by the transcription factor inducible cAMP early repressor (ICER)/cAMP response element modulator (CREM), which is known to be overexpressed in T cells both from patients with SLE or MRL/lpr lupus-prone mice." (PMID 33692797, 2021). "Activated cTfh cells showed increased SLC1A5 and GLS expression (but not GLUD1) (orange group), indicating active glutamine metabolism, known to be critical for Th17 cells and disease severity in lupus mice." (PMID 40693461, 2025).
medulloblastoma (5 papers, 2022 to 2025). A malignant, invasive embryonal neoplasm arising from the cerebellum. "This glutamine dependency makes Group 3 medulloblastomas especially sensitive to glutaminase inhibitors, which have shown potential in reducing tumor cell viability in preclinical studies." (PMID 40868156, 2025). "Mechanically, NEAT1 sponges miR-23a-3p to form a ceRNA network to regulate expression of the miR-23a-3p target, GLS, leading to cisplatin resistance in medulloblastoma." (PMID 35313796, 2022). "For instance, combining CB-839 (a glutaminase inhibitor) with decitabine has demonstrated improved efficacy in certain cancers, suggesting that similar strategies may be effective in medulloblastoma." (PMID 40868156, 2025). "This chemoresistance of medulloblastoma cells is mediated via the NEAT1/miR-23a-3p/GLS axis." (PMID 39010056, 2024). "In addition, glutamate was significantly positively correlated with GLS, which implies that glutamine to glutamate interconversion is an important regulator of the concentration of these metabolites in medulloblastoma." (PMID 38184938, 2024).
schizophrenia (5 papers, 2005 to 2021). A major psychotic disorder characterized by abnormalities in the perception or expression of reality. "This is in contrast to previous findings showing increases in glutaminase in the thalamus and in DLPFC of subjects with schizophrenia." (PMID 19772658, 2009). "Glutaminase, which converts glutamine to glutamate, was decreased in expression in glucose-deprived LCLs and decreased in expression in the DLPFC in subjects with schizophrenia compared to controls." (PMID 19772658, 2009).
Alzheimer disease (4 papers, 2019 to 2023). A progressive, neurodegenerative disease characterized by loss of function and death of nerve cells in several areas of the brain leading to loss of cognitive function such as memory and language. "Previous studies demonstrate abnormal elevation of glutaminase 1 (GLS1) in microglia in chronic CNS disorders including Alzheimer's disease and HIV-associated neurocognitive disorders." (PMID 32117296, 2020). "JHU083, a glutaminase inhibitor, was reported to attenuate behavioral deficits and improve disease outcomes in some neuroinflammation models, such as chronic social defeat stress and Alzheimer's disease." (PMID 35977050, 2022).
brain ischemia (4 papers, 2016 to 2024). Diminished or absent blood supply to the brain caused by obstruction (thrombosis or embolism) of an artery resulting in neurologic damage. "The present study also identified GLS as a hub gene associated with copper-induced cell death during cerebral ischemia." (PMID 39360273, 2024). "Eight hub genes (FDX1, LIPT1, LIAS, DLD, PDHA1, DLAT, PDHB, and GLS) were identified as potential core targets of cerebral ischemia." (PMID 39360273, 2024). "With the docking design to galangin, the six proteins (GLUD1, GLUL, GLS, CTH, GOT2 and HP) with high affinity might become its targets for cerebral ischemia." (PMID 27058522, 2016).
cholangiocarcinoma (4 papers, 2024 to 2026). A carcinoma that arises from the intrahepatic biliary tree (intrahepatic cholangiocarcinoma) or from the junction, or adjacent to the junction, of the right and left hepatic ducts (hilar cholangiocarcinoma). "Conversely, the emulation of glucose deprivation through the use of glutaminase (GLS) inhibitors increases the susceptibility of intrahepatic cholangiocarcinoma to chemotherapy, indicating the potential for metabolic modulation as an adjunct to conventional anticancer regimens." (PMID 39403606, 2024). "NSUN5 overexpression enhanced the growth and metastasis of cholangiocarcinoma cells by positive regulation of glutaminase expression." (PMID 41462962, 2025). "In gemcitabine-resistant cholangiocarcinoma (CCA) cells, curcumin synergistically downregulates the expression of glutaminase (GLS) and glutamine synthetase (GS) by inhibiting LAT2-mediated glutamine (Gln) uptake in conjunction with gemcitabine." (PMID 41515171, 2025). "In cholangiocarcinoma, NSUN5-mediated m5C modification is located at the 137 C site of the glutaminase mRNA sequence, stabilizing glutaminase mRNA and leading to the accumulation of intracellular glutaminase." (PMID 41462962, 2025).
Cirrhosis (4 papers, 2022 to 2023). A chronic disorder of the liver in which liver tissue becomes scarred and is partially replaced by regenerative nodules and fibrotic tissue resulting in loss of liver function. "Though levels of IL-6 and ammonia and alterations in the glutaminase gene have been reported as possible indicators of HE in patients with cirrhosis, they may not always be readily available within health care data sets." (PMID 37930150, 2023).
Cognitive impairment (4 papers, 2022 to 2025). Abnormal cognition is characterized by deficits in thinking, reasoning, or remembering. "Increasingly, JHU-083, a glutamine antagonist was found to alleviate AD pathogenesis and cognitive disorder induced by excess microglial LPS-induced glutaminase (GLS) in APOE 4 knock-in mice." (PMID 35558075, 2022). "Moreover, inhibition of glutaminase can block this process and improve cognitive impairment in AD." (PMID 41445867, 2025). "An examination into the role of amygdala glutamatergic neurons in sevoflurane's impact on cognitive impairments was conducted by administering buthionine sulfoximine (BSO), a substance that hampers the activity of glutaminase—an enzyme essential for the production of glutamate in neurons." (PMID 40376911, 2025).
endometrial cancer (4 papers, 2020 to 2024). Primary or metastatic malignant neoplasm involving the endometrium (mucous membrane that lines the endometrial cavity). "The expression of CDKN2A and GLS is also positively associated with the abundance of certain immune cells in endometrial cancer." (PMID 36588699, 2022). "High levels of estrogen affect glutathione metabolism by increasing the level of glutaminase, thereby inhibiting autophagy in endometrial cancer and promoting its growth." (PMID 33109128, 2020). "Subsequently, we treated the cells with CB-839 (1 μM), an inhibitor of GLS, and found that inhibition of GLS reduced proliferation, migration, and ATP production levels in endometrial cancer cells, while concurrent treatment with P4 further reduced these levels." (PMID 38415405, 2024).
endometriosis (4 papers, 2022 to 2026). The growth of functional endometrial tissue in anatomic sites outside the uterine body. "As expected, the expression of CDKN2A was upregulated, whereas the expression of GLS and LIPT1 was downregulated in UCEC cells versus normal human endometriosis cells." (PMID 35937995, 2022).
liver diseases (4 papers, 2015 to 2026). "These insights position Gls as a potential biomarker and therapeutic target in WD, warranting further investigation into its mechanistic role and the therapeutic implications of targeting glutaminase activity in copper‐associated liver diseases." (PMID 41230834, 2025). "Expanded repeats in the 5' untranslated region of the glutaminase (GLS) gene associated with stage 5 chronic kidney disease (odds ratio (OR) = 14.0 (5.7-34.3, 95% confidence interval (CI))) and liver diseases (OR = 3.0 (1.5-5.9, 95% CI))." (PMID 41501457, 2026). "Taken together, although many HCC patients co-exist liver disease and thus usually have impaired ammonia metabolism, GLS inhibition by CB-839 treatment is less likely to pose a problem for these patients." (PMID 33016874, 2020).
ovarian clear cell cancer (4 papers, 2022 to 2024). An invasive malignant neoplasm that arises from the ovary and is characterized by a predominance of clear and hobnail malignant epithelial cells. "GLS-1 inhibition alone or in combination with immune checkpoint blockade represents an effective therapeutic strategy for SWI/SNF-altered cancers such as ARID1A-mutated ovarian clear cell carcinoma." (PMID 38383406, 2024). "In ARID1A-inactivated ovarian carcinoma clear cell carcinoma (OCCC), the loss of ARID1A increases glutamine utilization and metabolism through upregulation of the expression of glutaminase (GLS1), a key enzyme in glutamine metabolism that is overexpressed in several human cancers." (PMID 36980292, 2023).
prostate tumor (4 papers, 2013 to 2025). "Additionally, glutamine is vital for the proliferation and growth of prostate epithelial cells, with increased glutamine uptake and upregulation of glutaminase observed in prostate tumor cells, enhancing glutamine metabolism." (PMID 41179286, 2025). "Inhibition of GLS with BPTES or genetic silencing of GLS or GLS2 increased the radiation sensitivity of lung and prostate tumor cell lines." (PMID 39199642, 2024).
pulmonary hypertension (4 papers, 2019 to 2026). Increased pressure within the pulmonary circulation due to lung or heart disorder. "In a rat pulmonary hypertension model, YAP promotes glutaminolysis through transcriptional activation of glutaminase (GLS1) in endothelia." (PMID 31380363, 2019).
sarcoma (4 papers, 2015 to 2024). A usually aggressive malignant neoplasm of the soft tissue or bone. "Finally, we evaluated a pharmacological inhibitor of glutaminase (CB-839) to verify the radiosensitization of sarcomas through glutaminase inhibition." (PMID 38769385, 2024). "Inhibitors of glutamine synthesis may be potential therapeutic options in the treatment of sarcomas that express high levels of glutaminase and are dependent on glutamine metabolism." (PMID 39659782, 2024). "However, we found that inhibition of glutaminase alone was insufficient to impact Nras-driven primary sarcoma growth and overall survival of mice." (PMID 38769385, 2024). "However, inhibition of glutaminolysis in Gls1fl/fl sarcomas did not impact time to tumor quintupling and overall survival compared to Gls1+/+ or Gls1fl/+ sarcomas, suggesting that deletion of glutaminase alone was insufficient to reduce sarcoma growth." (PMID 38769385, 2024). "Taken together, these data suggest that pharmacological targeting of glutaminase could improve sarcoma radiation response." (PMID 38769385, 2024). "Interestingly, we also revealed that inhibition of glutaminase radiosensitized autochthonous sarcomas in vivo, which might be mediated by the innate immune response." (PMID 38769385, 2024). "However, further studies are necessary to define critical GLS regulatory pathways in sarcomas." (PMID 31980651, 2020). "In summary, GLS upregulation promotes glutamine utilization to sustain the TCA cycle and maintain energetic as well as biosynthetic demands in sarcoma cell growth and proliferation." (PMID 31980651, 2020). "Consistent with this notion, we found that glutaminase expression was increased by 7- to 11-fold in mouse sarcoma cells compared to normal mouse muscle, suggesting that this mechanism may be used by sarcoma cells to counteract glutamate reductions that may result from ASNS silencing." (PMID 26499495, 2015). "We verified that glutaminase expression at the protein level was negligible in Gls1fl/fl sarcomas compared to Gls1+/+ sarcomas, regardless of RT status." (PMID 38769385, 2024).
type 2 diabetes (4 papers, 2012 to 2023). "Moreover, lactulose breath test was found altered in 8 out of 9 patients with previous bouts of hepatic encephalopathy; c) type 2 diabetes seems to play a role modulating several isoforms of glutaminase (GA)." (PMID 23166628, 2012).
viral infections (4 papers, 2020 to 2024). "Both OC43 and GLS expression levels in HBECs showed significant increases between 12 and 48 h of virus infection." (PMID 39662828, 2024). "In HCT8 cells, GLS protein expression was modestly increased (1.7-fold) with virus infection, whereas GLS2 protein levels were not changed." (PMID 39662828, 2024). "Our observed 1.5-fold increase in GLS activity following viral protein overexpression and our 1.75-fold increase in GLS activity during MNV infections is consistent with previously published results showing 1.25–1.5-fold increases in metabolic enzyme activity during viral infections." (PMID 38976719, 2024). "For instance, therapeutics inhibition of glutamine transporters or GLS enzyme can also be used as an effective method against glutamine-dependent viral infections, irrespective of the precise need for glutamine, as they will block all the metabolic pathways that require glutamine." (PMID 33585567, 2020).
B cell lymphomas (3 papers, 2017 to 2025). "To evaluate the dependence of PCLP-induced B-cell lymphoma cell proliferation on glutaminolysis, we tested its sensitivity to Compound 968, a selective inhibitor of glutaminase 1 (GLS1)." (PMID 29245936, 2017). "Despite this, recent findings provide evidence that the glutaminase activity of ASNases is important for the cytotoxic effects on B-ALL cells, as mutant ASNases with abolished glutaminase activity were significantly less cytotoxic to B cell lymphomas when compared to WT ASNases." (PMID 39102101, 2024).
benign prostate hyperplasia (3 papers, 2021 to 2024). "Immunohistological examination of the GLS protein expression in human prostatic specimens confirmed that it is highly expressed in PCa compared to benign prostate hyperplasia (BPH) tissues." (PMID 39199642, 2024).
brain cancer (3 papers, 2020 to 2024). A primary or metastatic malignant neoplasm affecting the brain. "In many cancer types, including breast, lung, prostate, and brain cancers, there is evidence of increased glutaminase expression compared to normal tissues." (PMID 39170262, 2024). "Moreover, increased GLS expression has been correlated with higher grade brain cancers, shortened patient survival, and temozolomide (TMZ) resistance." (PMID 32337072, 2020).
brain tumors (3 papers, 2019 to 2022). "GLS activity corresponds with poor clinical prognosis in patients with breast, colorectal, lung, liver, and brain tumors, and rapid-growing tumor cells have enhanced GLS mRNA levels as well as elevated GLS expression." (PMID 35956989, 2022).